REN (renin)
Diseases named in the same sentence as REN in open-access papers (continued):
Sharing a sentence is not in itself a finding about the gene and the disease.
heart failure (continued). "Treatment of heart failure with reduced ejection fraction, the clinical correlate of the animal models used to investigate heart failure, is largely based on medications that reduce the detrimental activation of the renin–angiotensin–aldosterone and sympathetic nervous system." (PMID 32748289, 2020). "The Chinese herbal formula SNT could improve left ventricular systolic function in heart failure after myocardial infarction in rats and decreased the level of Plasma Renin, Angiotensin II, and Aldosterone, as well as downregulating the protein and gene level of ACE and AT1R." (PMID 30050591, 2018). "Indeed, these findings may have implications beyond neurogenic hypertension and may offer benefit in other diseases of sympathetic overactivity, such as modulation of renin–angiotensin–aldosterone release, chronic inflammatory diseases, and heart failure." (PMID 29686017, 2018). "Furthermore, from a philosophical viewpoint the chronic activation of the adaptive stress pathways that lead to the activation of p38 MAPKs in heart failure is analogous to the chronic activation of the sympathetic, renin-aldosterone-angiotensin and neprilysin systems." (PMID 26029107, 2015). "Activation of the renin–angiotensin–aldosterone system (RAAS) and increased activity of the sympathetic nervous system are important elements of the pathophysiology of heart failure after myocardial infarction." (PMID 41007826, 2025). "Hyperkalaemia is a barrier to achieving optimal, guideline-directed treatment with renin–angiotensin–aldosterone system inhibitors (RAASis) in patients with chronic kidney disease (CKD) and/or heart failure (HF)." (PMID 38253386, 2024). "This occurs, for instance, in patients with heart failure, particularly during treatment with RAS blockers and diuretics (with high renin levels), and it also occurred in the SHR of the present study, both in blood and hepatic tissue sites." (PMID 38690653, 2024). "After developing left ventricular dysfunction, activation of both the renin–angiotensin–aldosterone system (RAS), and the SNS happens as a response to heart failure-induced hypoperfusion." (PMID 39125627, 2024). "In terms of neuroendocrine hormones, the renin-angiotensin-aldosterone system (RAAS) and sympathetic nervous system are activated in patients with heart failure." (PMID 39717447, 2024). "Concurrently, renin, angiotensin II (Ang-II), and aldosterone (ALD) related to heart failure, elevated in the MI group compared to the control group 4 weeks post-MI." (PMID 39266583, 2024). "Renin-angiotensin system acting agents were used by 35.6% of all patients, but by more than 90% of patients with CKD or heart failure." (PMID 36289275, 2022). "Notably, targeting of the CXCL10/CXCR3 axis in addition to cardiac inflammation may constitute a new pharmacological approach for either heart failure or CAD therapy supplementary to present drugs that typically target the sympathetic or renin-angiotensin system or platelets." (PMID 34835155, 2021). "Chronic renin-angiotensin-aldosterone system (RAAS) activation in course of heart diseases contributes to cardiac remodeling and heart failure." (PMID 33413406, 2021). "The myocardial fibrosis occurs due to molecular mechanisms that activate the renin-angiotensin-aldosterone system which in turn promotes TGF-β expression and eventually heart failure." (PMID 32064281, 2020). "The activation of the renin-angiotensin system (RAS) participates in the development of metabolic syndrome (MetS) and in heart failure." (PMID 33354204, 2020). "Although the PRA of WT or CSQ‐tg mice was comparable or slightly higher than that in healthy subjects and heart failure patients 19, 20, triple‐tg mice had much higher PRA due to overexpression of human renin and human angiotensinogen." (PMID 32056390, 2020).
heart failure (continued). "Blockade of the renin–angiotensin system (RAS) is well-known to be beneficial in preserving heart and kidney function in those with heart failure, postmyocardial infarction and kidney disease." (PMID 32245239, 2020). "It is widely accepted that renin-angiotensin-aldosterone system (RAAS) is activated in myocardial ischemia and heart failure." (PMID 31647035, 2019). "This study evaluated molecular and ultrastructural adaptations in experimental progressive heart failure, and analyzed the effects of a combined inhibition of the renin-angiotensin system and neprilysin (RAS-/NEP-inhibition) on overt heart failure." (PMID 28076404, 2017). "Animal models have suggested a role of renin-angiotensin system (RAS) activation and subsequent cardiac oxidation in heart failure with preserved ejection fraction (HFpEF)." (PMID 26504834, 2015). "In heart failure (HF) there is an increase in renal sympathetic nerve activity (RSNA), which can lead to renal vasoconstriction, increased renin release and sodium retention." (PMID 26483699, 2015). "The renin–angiotensin system (RAS) is a central regulator of cardiovascular and renal functions and plays an important role in the pathophysiology of heart failure." (PMID 24691269, 2014). "Myocardial fibrosis, a major pathophysiologic substrate of heart failure with preserved ejection fraction (HFPEF), is modulated by multiple pathways including the renin-angiotensin system." (PMID 24349097, 2013). "Activation of the renin-angiotensin system (RAS) plays a critical role in the pathophysiology of myocardial infarction (MI) and the development of heart failure." (PMID 24134599, 2013). "Accumulating evidence suggests that the local cardiac renin-angiotensin system (RAS) is involved in the development and progression of cardiac hypertrophy, remodeling, and heart failure." (PMID 24204720, 2013). "This was the essential experiment for proving the role of Renin- Angiotensin- Aldosterone System (RAAS) in the process of remodeling and progression of cardiac failure." (PMID 20108509, 2008). "In cases of reduced LV systolic function, standard heart failure GDMT typically includes beta-blockers, renin–angiotensin system blockade with angiotensin-converting enzyme inhibitors, angiotensin receptor blockers, or a neprilysin inhibitor–angiotensin receptor combination (sacubitril/valsartan)." (PMID 40564045, 2025). "Fibroblasts, among the most abundant cell types in the heart, are crucial to cardiac fibrosis, which contributes cardiac remodeling, arrhythmias, and heart failure under pathological stimuli such as inflammatory cytokines, ROSs, TGF-β, and the renin–angiotensin–aldosterone system." (PMID 39195221, 2024). "It has also been shown that CFEVs can target angiotensin II receptor type 1 (AT1R) and 2 (AT2R) and chronic activation of the myocardial renin-angiotensin system (RAS), leading to increased levels of angiotensin II (Ang II), which also contributes to cardiac hypertrophy and heart failure." (PMID 38543275, 2024). "B-type natriuretic peptide (BNP) and the amino-terminal fragment of its prohormone (NT-proBNP) are commonly used for heart failure screening and diagnosis, but biologically BNP exerts several beneficial cardiovascular effects primarily by counteracting the renin-angiotensin-aldosterone-system." (PMID 39097697, 2024). "All groups showed a decreasing trend in renin levels, suggesting that CRAT preventative treatment might inhibit the production of AngII, thereby alleviating heart failure." (PMID 38675456, 2024). "Second, the renin-angiotensin-aldosterone system (RAAS) to may be activated by IR, which results in cardiac insufficiency." (PMID 36875470, 2023). "Unlike the renin–angiotensin system and the sympathetic nervous system, the role of the vasopressin system in the development of heart failure is understudied." (PMID 36674841, 2023).
heart failure (continued). "One of the commonest reported mechanisms is the simultaneous modulatory effects on calcium homeostasis and its role on major neurohormonal regulatory systems such as renin–angiotensin–aldosterone system (RAAS) and natriuretic peptide system (overactivated in heart failure patients)." (PMID 36184714, 2023). "For patients with cancer and heart failure with reduced ejection fraction (HFrEF), ACEI is the most common renin-angiotensin-aldosterone system (RAAS) inhibitor prescribed by the respondents, followed by angiotensin receptor-neprilysin inhibitor (ARNI) (17.1%) and ARB (16.4%)." (PMID 36211547, 2022). "The renin-angiotensin-aldosterone system (RAAS) is a key component of the neurohormonal axis responsible for maintaining blood pressure by modulating intravascular volume, salt retention, and vascular tone—all central mechanisms of disease in heart failure." (PMID 35620081, 2022). "In this study, we generated human renin, human angiotensinogen, and canine calsequestrin transgenic (triple‐tg) mice, and then investigated the cardioprotective effect of TAK‐272 in this model in addition to its heart failure phenotypes." (PMID 32056390, 2020). "Whereas the inhibition of the renin–angiotensin–aldosterone pathway is an established therapy in heart failure, the role of IL-6 has not been fully elucidated." (PMID 33122738, 2020). "In healthy subjects, as opposed to heart failure patients, high plasma volume potentially inhibits renin secretion." (PMID 32817643, 2020). "In line with this, a recent study in heart failure with reduced ejection fraction patients also showed that ACE2 was higher in male than female patients, independent of the use of pharmacological therapies targeting the renin–angiotensin–aldosterone system." (PMID 32831121, 2020). "The plasma level of the renin is increased in patients with heart failure as a result of neurohumoral changes that are activated in heart failure; this usually leads to negative consequences in overall health conditions." (PMID 31053170, 2019). "Recently, several randomized studies showed a negative or modest effect of heart failure drugs such as beta blockers or angiotensin-renin system inhibitors in preventing cardiotoxicity." (PMID 31869400, 2019). "Maybe the question that we should keep asking ourselves is that what is the best level of controlling renin and RAAS system, so as to improve the prognosis of heart failure patients to the maximum extent?" (PMID 29152151, 2017). "The renin-angiotensin system (RAS) and its primary effector peptide, angiotensin II (Ang II), is a key regulatory system in blood pressure and volume homeostasis and has an essential role in the pathophysiology of heart failure." (PMID 26237391, 2014). "Renin-angiotensin system inhibitors (RAS) inhibitors include angiotensin receptor blockers (ARBs) and angiotensin-converting enzyme (ACE) inhibitors decrease proteinuria, progression of chronic kidney disease (CKD), and protect against heart failure hospitalizations and cardiovascular events." (PMID 37214072, 2023). "Diminished intravascular volume.Heart failure.Intravascular/ Interstitial fluid imbalance.Glycocalyx derangements.ECMO-related nonpulsatile blood flow.Ischemia-reperfusion related injury.Renin-angiotensin, sympathetic system and natriuretic peptides disbalance." (PMID 37674997, 2022). "Treatment with these drugs anticipate a compensatory up-regulation of renin; however, it has been shown that there is a large variability in circulating plasma renin (PRA), even in patients with optimal medical therapy in patients with heart failure (HF) with reduced ejection fraction (HFrEF)." (PMID 34063595, 2021). "SNT improves cardiac function by inhibiting the excessive activation of the renin-angiotensin-aldosterone system, which involves a reduction in the levels of plasma angiotensin II and downregulation of the protein and gene levels of AT1R in heart failure after myocardial infarction in rats." (PMID 34195269, 2021).
heart failure (continued). "Indeed, our data suggest that the TAC model is suitable to test the function of novel proteins in or therapeutics for heart failure without an influence of kidney dysfunction other than renin release." (PMID 34211391, 2021). "Drugs affecting the renin–angiotensin–aldosterone axis, such as ACE inhibitors, angiotensin receptor blockers, or mineralocorticoid receptor blockers, are used as the primary means of treatment in patients with heart failure and reduced ejection fraction, including those with DCM." (PMID 32599970, 2020). "Induction of heart failure in rats has significantly increased circulating NT-proBNP (980 ± 116.71 pg/ml), MMP9 (15.85 ± 0.57 ng/ml), troponin-I (3.09 ± 0.147 ng/ml), CK-MB (31.55 ± 1.69 ng/ml), renin (736 ± 45.8 pg/ml), urea (52.1 ± 1.57 mg/dl), and creatinine (0.92 ± 0.04 mg/dl)." (PMID 31053170, 2019). "Our result was also consistent with the previous reports that aliskiren showed cardioprotective effects without lowering blood pressure in normotensive heart failure mice, despite showing remarkable increase in cardiac renin concentration due to renin inhibition." (PMID 30092100, 2018). "Moreover, drug-induced suppression of renin synthesis does not improve survival in patients with heart failure." (PMID 30057603, 2018). "In other words, it's critical to know whether or not there is an optimal inhibition of renin level so as to achieve the best outcomes for heart failure patients." (PMID 29152151, 2017). "It is considered to be a factor in virtually every form of CHD, and therapeutic strategies that block renin-angiotensin system activation using either ACEI or angiotensin receptor blockers favorably affect remodeling and reduce morbidity and mortality in post-MI and heart failure patients." (PMID 23304234, 2012). "Additionally, selected renin–angiotensin–aldosterone system (RAAS) components, including renin, angiotensin II, and atrial natriuretic peptide, are higher in dogs with severe heartworm disease than in healthy dogs, supporting a role for the RAAS in advanced disease with heart failure." (PMID 37106412, 2023). "Furthermore, the use of SGLT2i was associated with greater reductions in new-onset AF events in subgroups including those without previous history of heart failure, those with a BMI of < 25 kg/m2, and those without concomitant use of renin-angiotensin system blockers (P interaction < 0.05)." (PMID 33158436, 2020). "Additionally, recent findings suggest that increased plasma renin activity induced by MRBs, without concurrent RAS inhibition, may be associated with reduced muscle mass in patients with heart failure, although muscle wasting and LVMI reduction are distinct phenomena." (PMID 40588503, 2025).
Insulin resistance (363 papers, 2006 to 2026). Increased resistance towards insulin, that is, diminished effectiveness of insulin in reducing blood glucose levels. "Mechanisms linking the AIP to all-cause and CVD mortality involve atherosclerosis, insulin resistance (IR), oxidative stress, and renin–angiotensin–aldosterone system (RAAS) activation." (PMID 40725725, 2025). "Aldosterone and renin were positively associated with insulin resistance and hyperglycemia, and negatively impacted glucose metabolism." (PMID 40106408, 2025). "For example, the use of ACEIs and ARBs can alleviate insulin resistance, which is considered a risk factor for the prostate, through the renin-angiotensin system." (PMID 38487860, 2024). "Several studies have confirmed a significant clustering between elevated uACR and traditional risk factors for HF, which include insulin resistance, inflammatory response, and renin-angiotensin- aldosterone system (RAAS) activation." (PMID 36966320, 2023). "Hyperglycemia and insulin resistance can activate the renin–angiotensin–aldosterone system and increase the risk of CVD." (PMID 34980154, 2022). "HTN patients usually have metabolic syndrome caused by insulin resistance and hyperactivity of the sympathetic tone, which can activate the renin–angiotensin–aldosterone system and promote atherosclerosis development." (PMID 34980154, 2022). "Insulin resistance can cause renal injury through renin-angiotensin system activation, increases in aldosterone and angiotensin II with subsequent effects on endothelin-1 and insulin-like growth factor-1, and the generation of reactive oxygen species." (PMID 35885048, 2022). "Second, insulin resistance has been associated with the increased sympathetic nervous system and renin–angiotensin–aldosterone system activity; both of them were involved in myocardial fibrosis and cardiac dysfunction." (PMID 34222388, 2021). "Weight loss, RAAS (renin–angiotensin–aldosterone system) blockade and improvement of insulin resistance can relieve ORN to some extent, which also has many limitations." (PMID 34711178, 2021). "Renin concentrations, on the other hand, were associated most strongly with glucose levels and insulin resistance, confirming previous reports." (PMID 32529242, 2020). "ADRB1 also contributes to increased secretion of renin and ghrelin hormones, which are associated with T2D and insulin resistance." (PMID 33113859, 2020). "The reported improvements in systemic insulin resistance, insulin signaling and glucose uptake in skeletal muscle by renin inhibition were associated with decreases in the levels of Ang II, aldosterone, AT1R, oxidative stress, and fibrosis." (PMID 32235782, 2020). "Visceral obesity associated with insulin resistance leads not only to compensatory hyperinsulinemia but also to inadequate activation of the renin-angiotensin system and oxidative stress to the kidney." (PMID 24876964, 2014). "Another factor associated with insulin resistance in chronic kidney disease is Ang II where there is activation of the renal renin-angiotensin system." (PMID 23431467, 2013). "For daytime sleeping, the increased sympathetic activity on awakening from naps results in activation of the renin-angiotensin system, which is suggested to modulate insulin resistance and associated hyperglycemia." (PMID 22829819, 2012). "We also look into plausible biological explanations for such an association with the renin-angiotensin-aldosterone system and insulin resistance playing potential roles." (PMID 20049157, 2010). "Furthermore, elevated renin expression has been associated with increased aldosterone production, further compounding insulin resistance and impairing glucose metabolism." (PMID 40564980, 2025). "Notably, aldosterone and renin were positively associated with insulin resistance and hyperglycemia, and detrimentally impaired glucose metabolism." (PMID 40106408, 2025).